ABCG2 (ATP binding cassette subfamily G member 2 (JR blood group))
Diseases named in the same sentence as ABCG2 in open-access papers (continued):
Sharing a sentence is not in itself a finding about the gene and the disease.
digestive system cancer (2 papers, 2023 to 2025). A primary or metastatic malignant neoplasm involving any part of the digestive system. "Significantly increased expression of ABCG2 was observed in so-called side population (SP) cells isolated from various human gastrointestinal system cancer cell lines resembling stem cells." (PMID 37445716, 2023). "Breast cancer resistance protein (BCRP, also known as ABCG2) belongs to the ATP-binding cassette G family and plays a significant role in the efflux of various anticancer drugs, thereby contributing to the development of chemoresistance, particularly in digestive system cancers." (PMID 40830621, 2025).
gynecologic tumors (1 paper, 2017). "Interestingly, by utilizing the resources of TCGA database, we found that the mean expression level of ABCG2 in clear cell RCC is highest compared to all the other genitourinary and gynecologic tumors (p < 0.001)." (PMID 28347288, 2017).
inflammation (1 paper, 2022). Aberrant reaction of the microcirculation characterized by movement of fluid and leukocytes from the blood into extravascular tissues. "In studies of intestinal inflammation, soluble uric acid increased the expression of PDZK1 and ABCG2." (PMID 36052278, 2022).
ABCG2 also shares sentences with these, for which no sentence is quoted: Pseudoxanthoma elasticum (9 papers); atherosclerosis (7); type 2 diabetes (7); amyotrophic lateral sclerosis (5); iron deficiency (5); colitis (4); ischemic stroke (4); neurodegenerative disease (4); asthma (3); benign tumor (3); Dubin-Johnson syndrome (3); fibrosarcoma (3); Hand-foot syndrome (3); Hodgkins lymphoma (3); liver dysfunction (3); Parkinson disease (3); pneumonia (3); systemic lupus erythematosus (3); Tangier disease (3); ulcerative colitis (3); acne (2); acute liver failure (2); adrenocortical carcinoma (2); adrenoleukodystrophy (2); African trypanosomiasis (2); basal cell carcinoma (2); blood cancers (2); celiac disease (2); chronic lymphocytic leukemia (2); CNS tumors (2).
A further 178 diseases each share a sentence with ABCG2 in 2 papers or fewer.